SOD2 (superoxide dismutase 2)
Diseases named in the same sentence as SOD2 in open-access papers (continued):
Sharing a sentence is not in itself a finding about the gene and the disease.
Stroke (21 papers, 2009 to 2025). Sudden impairment of blood flow to a part of the brain due to occlusion or rupture of an artery to the brain. "The T allele of the c.47T > C—SOD2 SNP were positively corelated with stroke (bootstrap crude OR 1.31; 1.07–1.59 95% CI; statistical power (SP) 0.490), while the C allele showed a negative correlation (bootstrap crude OR 0.76; 0.62–0.93 95% CI; SP 0.582)." (PMID 33808851, 2021). "Mitochondrial antioxidant systems are critically involved in neurodegenerative disorders in which ROS toxicity is a major pathogenic factor, and SOD2 has been claimed to participate in the progression of neurodegenerative disorders such as stroke and Alzheimer and Parkinson diseases." (PMID 41372147, 2025). "SOD-2 mutations are related to the onset of AD, Parkinson’s disease, and stroke." (PMID 35203488, 2022). "The c.47T > C (rs4880) polymorphism of the SOD2 gene and stroke risk." (PMID 33808851, 2021). "In stroke, SOD2 genetic variant may alternatively predict the risk of stroke in patients with sickle cell anemia, and SOD2 mutation exacerbates ischemic brain damage under hyperglycemic condition." (PMID 34790286, 2021). "In addition, SOD2 has been implicated in mitochondrial dysfunction and examined for its role in models of neurodegenerative diseases including stroke, ALS, and Parkinson's, Alzheimer's, and Huntington's Diseases." (PMID 24406377, 2014). "Together with direct interactions between miR-574-5p and circPHKA2 or SOD2, these data revealed a circPHKA2-miR-574-5p-SOD2 ceRNA axis in stroke-induced neurovascular injury." (PMID 36830585, 2023). "Eventually, a circPHKA2-microRNA (miR-574-5p)-SOD2 axis was highlighted, and miR-574-5p is recommended as one of the markers for stroke diagnosis by interacting with multiple messenger RNAs (mRNAs) of stroke candidate genes." (PMID 34790286, 2021). "Coupled with direct interactions between miR-574-5p and circPHKA2 or SOD2, these data together revealed a circPHKA2-miR-574-5p-SOD2 ceRNA axis in stroke-induced neurovascular damage." (PMID 34790286, 2021). "Other SNPs in genes involved in inflammation (APOE and IL6), oxidative stress (NOS3 and SOD2), and As metabolism (AS3MT, CBS, GSTO1, and MTHFR) showed nominally significant interactions with well-water As for associations with CVD, CHD, or stroke." (PMID 25575156, 2015). "Our lab showed that knocking-down miR-145, a highly stroke-induced miRNA increases the expression of its down-stream target superoxide dismutase-2 with concomitant neuroprotection in rats subjected to transient MCAO." (PMID 23516428, 2013). "We hypothesize that single nucleotide polymorphisms (SNPs) in the SOD2, CAT, GPX4, NOS1 and NOS2 genes might be associated with altered susceptibility to oxidative stress and stroke development." (PMID 33808851, 2021). "At the time of stroke, rats treated with LV-UCP2 still showed a large UCP2 upregulation in the striatum, associated with increases in OPA1 and FIS1 protein levels, and reductions in PGC1-α, SOD2, TNFα mRNA levels and NRF2 protein levels." (PMID 32560241, 2020). "Meanwhile, especially after reperfusion of stroke, too much ROS could be generated, which may injure mitochondria and consume SOD2." (PMID 31662771, 2019). "Therefore, ameliorating mitochondrial functions and increasing SOD2 level are regarded to be effective in treating stroke." (PMID 31662771, 2019). "In conclusion, our results showed that the genetics variants in the SOD2 (c.47T > C; rs4880), GPX4 (c.660T > A; rs713041), NOS1 (g.117803515C > T; rs1879417) and NOS2 (c.1823C > T; rs2297518 and c.-227G > C; rs10459953) genes may be associated with individual susceptibility to a stroke." (PMID 33808851, 2021). "After stroke, dBET1 dramatically reduced oxidative damage levels revealed by decreased 4-HNE, a lipid peroxidation product, and gp91phox, a major source of oxygen radical generation, and improved the expression levels of antioxidant enzymes SOD2 and GPx1." (PMID 35761277, 2022).
Stroke (continued). "dBET1 markedly reduced inflammation and oxidative stress after stroke, indicated by multiple pro-inflammatory cytokines and chemokines including IL-1β, IL-6, TNF-α, CCL2, CXCL1 and CXCL10, and oxidative damage markers 4-hydroxynonenal (4-HNE) and gp91phox and antioxidative proteins SOD2 and GPx1." (PMID 35761277, 2022).
coronary artery disease (20 papers, 2008 to 2025). "This has not been confirmed by another study focused on the role of antioxidative enzymes (including SOD2) in determining genetic susceptibility to the coronary artery disease in patients with T2DM." (PMID 18423055, 2008). "Another study showed that the alanine variant increased the activity of SOD2 and its ability to neutralize the superoxide free radicals in leukocytes, thereby decreasing oxidized low density lipoprotein and the associated risk of coronary artery disease and myocardial infraction." (PMID 37698290, 2023). "This highlights the vital role of SOD2 in ischemic heart disease therapy, governed by SIRT3 regulation." (PMID 39458930, 2024). "In a study in humans, the single Ala16Val SOD2 polymorphism has been investigated as associated with coronary heart disease (CHD) risk, in concomitance with decreased SOD2 activity and increased mtROS production." (PMID 35205167, 2022). "ADMA also impairs the migratory capacity of angiogenic progenitor cells (APCs) in patients with coronary artery disease through a micro RNA-21-dependent mechanism, inhibiting superoxide dismutase 2 in APCs." (PMID 26790728, 2016). "Patients with coronary artery disease demonstrated elevated expression of SOD1 and SOD2 but not SOD3." (PMID 38389898, 2024).
Parkinson disease (20 papers, 2011 to 2025). A progressive degenerative disorder of the central nervous system characterized by loss of dopamine producing neurons in the substantia nigra and the presence of Lewy bodies in the substantia nigra and locus coeruleus. "Administering functional SOD2 may be beneficial to Parkinson’s disease patients in reducing the OS immunopathology associated with the NG of these patients." (PMID 38214013, 2024). "Dopamine itself undergoes auto-oxidation and is an unstable molecule forming quinones and R•s.68,69 SOD2 enzyme activity is modified by dopamine quinones and has implications for Parkinson’s disease." (PMID 38214013, 2024). "Moreover, CLPP is helpful in reducing αSyn-induced mitochondrial oxidative stress in Parkinson’s patients by increasing the expression of superoxide dismutase-2 (SOD2)." (PMID 36834738, 2023).
COVID-19 (19 papers, 2021 to 2025). A disease caused by infection with severe acute respiratory syndrome coronavirus 2. "COVID-19 patients homozygous for variant SOD2*Val/Val genotype, had increased levels of both fibrinogen (p = 0.040) and ferritin (p = 0.033)." (PMID 35361071, 2022). "Our data aligns with these findings, since we found that COVID-19 patients with less efficient SOD2*Val variant presented higher susceptibility to the inflammatory process." (PMID 35361071, 2022). "Our data align with these findings, since we could hypothesize that in COVID-19 patients, carriers of SOD2*T genetic variant during SARS-CoV-2 infection with larger inflammatory damage to cardiomyocytes was present." (PMID 37373377, 2023). "Polymorphisms of SOD2 and GPX1 influenced COVID-19 patients’ laboratory biochemical profile: SOD2*Val allele was associated with increased levels of fibrinogen (p = 0.040) and ferritin (p = 0.033), whereas GPX1*Leu allele was associated with D-dimmer (p = 0.009)." (PMID 35361071, 2022). "Variants such as SOD2 rs4880, GSTP1, GSTO1, PON1, and NOS3 have been associated with reduced enzymatic activity, impaired detoxification of ROS, and worsened COVID-19 severity or post-acute sequelae." (PMID 41209585, 2025). "Immunohistochemical analyses of the inflammatory vital organs of patients who died from COVID-19 have shown increased levels of mitochondrial superoxide dismutase (SOD2) in the vital organs, but reduced levels in the lungs." (PMID 38464514, 2024). "The expression levels of Nrf2, CAT, SOD1, and SOD2 were increased in COVID-19 patients compared to healthy subjects." (PMID 36493512, 2023). "SOD2 is known as a gene whose expression variation has been confirmed accompanied with ICAM1 in COVID-19." (PMID 37719701, 2023). "Remarkably, the results indicated decreased expression of Nrf2, CAT, SOD1, and SOD2 (P-value <0.02) as well as GP91PHOX (P-value <0.02) in COVID-19 patients compared to controls." (PMID 36493512, 2023). "The second phase of clinical trials of the effects of SOD2 mimetics in patients with COVID-19 is underway." (PMID 35361071, 2022). "Immunohistochemical studies have shown that COVID-19 increases the level of the primary antioxidant enzyme, i.e., manganese superoxide dismutase (SOD-2), in cells of vital organs, including the kidneys." (PMID 36014561, 2022). "On the other hand, immunohistochemical studies showed a higher level of the SOD-2 isoenzyme in the cells of vital organs, including the kidneys, and a lower level in the cells of the lungs, a critical organ in the course of COVID-19." (PMID 36014561, 2022). "The reduction in Mn may impair SOD2 activity, potentially contributing to the OS and inflammation seen in COVID-19." (PMID 41209585, 2025). "However, when analyzed in combination with SOD2 rs4880 and CAT rs1001179, this SNP contributes to a significant three-locus interaction, increasing the risk of severe COVID-19 (OR ≈ 3.81, p ≈ 0.000055)." (PMID 41209585, 2025). "Furthermore, the influence of SOD2 and GPX1 polymorphisms on the inflammation and coagulation parameters in COVID-19 patients was also found." (PMID 37373377, 2023). "Furthermore, SOD2 is decreased in low-density neutrophils, which correlates with hypercoagulation and COVID-19 severity." (PMID 35159254, 2022). "Additionally, we have found that polymorphisms of SOD2 rs4880 and GPX1 rs1050450 influence COVID-19 patients’ laboratory biochemical profile." (PMID 35361071, 2022). "Furthermore, we have shown the influence of SOD2 and GPX1 polymorphisms on the inflammation and coagulation parameters in COVID-19 patients." (PMID 35624818, 2022). "For instance, while reducing the correlation between DEGs including IL10, CXCL8, NFKB1, ARG1, and SOD2, new strong associations appeared between ELANE, DEFA4, AZU1, CTSG, and LCN2, with an overall tendency to higher relationships amid neutrophil-mediated immunity genes in COVID-19 patients." (PMID 35269470, 2022).
COVID-19 (continued). "Our findings regarding the influence of SOD2 and GPX1 polymorphisms on the laboratory biochemical parameters might be of clinical importance, since we found that COVID-19 patients with low-activity alleles of these genes have higher levels of inflammation and coagulation parameters." (PMID 35361071, 2022). "Specifically, individuals with the SOD1 G, SOD2 T, and CAT C combination had higher odds of severe COVID-19 (p = 0.0045; OR = 2.84), suggesting a collective, rather than isolated, influence of these antioxidant genes." (PMID 41209585, 2025). "Among them, Superoxide Dismutase 2 (SOD2, P04179) and TEK Receptor Tyrosine Kinase (TEK, Q02763) have been confirmed as drug targets for COVID-19." (PMID 39192889, 2024). "Further detailed searches for the differential expression of 4-HNE and SOD2 might be a target for future research aiming to better understand the interference between lipid peroxidation and inflammatory cells generating vascular and systemic oxidative stress in lethal COVID-19." (PMID 35159254, 2022). "Neurological examination and antioxidant genetic profile (SOD2, GPXs and GSTs) determination, as well as, genotype analysis of Nrf2 and ACE2, were conducted on 167 COVID-19 patients." (PMID 35624818, 2022). "Lung cells from COVID-19 patients show expression of HIF1α, TLR2, TLR4, PFKFB3, CXCR1, −2 and −4, SOD2, PLAUR and other genes expressed in immature myeloid cells." (PMID 33345622, 2021). "SOD2 and GPX1 genotypes independently did not seem to significantly affect the risk for COVID-19 development as well." (PMID 35361071, 2022). "The examined polymorphisms of Nrf2, SOD2, GPX1 and GPX3 in our study also did not have association with severity of COVID-19 (Table A1)." (PMID 35361071, 2022). "Due to their differential expressions in blood vessels, inflammatory cells, and the kidneys, we think that SOD2 could, together with 4-HNE, be a potential link between a malfunctioning immune system, oxidative stress, and vascular stress in lethal COVID-19." (PMID 35159254, 2022). "In addition, some mito-DEGs were reversely altered in the AT2 and AT1 subsets (e.g., LRRK2, PID1, SOD2, CLIC4, and ERBB4) or showed altered expression in the AT2 or AT1 subset in patients with COVID-19 (–D)." (PMID 35844544, 2022). "MiRNAs that were downregulated in serum of COVID-19 patients mainly target genes promoting angiogenesis (e.g., VEGFA, ANGPT2, COL4A1, FGF2, ZEB1), apoptosis, autophagy, stress response (e.g., ATG12, ATG14, ATG2B, SOD2, TXNIP), and inflammation (e.g., CXCL9, CXCL10, IL1R1, TNF)." (PMID 36032130, 2022). "Moreover, following SARS-CoV-2 infection, both mitochondrial superoxide dismutase (SOD2) and heme oxygenase-1 (HO-1) were found to be altered, but their involvement in the pathogenesis of COVID-19 is not clear." (PMID 35159254, 2022).
metabolic syndrome (19 papers, 2012 to 2025). A cluster of metabolic risk factors for CARDIOVASCULAR DISEASES and TYPE 2 DIABETES MELLITUS. "A case–control study using occupational stress as a variable to investigate the role of SOD2 rs4880 in Han Chinese miners with dyslipidemia found that the condition was associated with occupational stress and genetic factors." (PMID 38275640, 2023). "In SOD2 rs4880 recessive model, patients with GG genotype had a lower risk of dyslipidemia than those with AA/AG genotype, and the difference was statistically significant." (PMID 36759651, 2023). "This study uses OS and genes (LYPLAL1, APOC3 and SOD2) as research variables, and explores their association with dyslipidemia in coal workers from the perspective of the interaction between environment and genetics." (PMID 36759651, 2023). "Low IRAK3 and high SOD2 was associated with a high prevalence of metabolic syndrome (odds ratio: 9.3; sensitivity: 91%; specificity: 77%)." (PMID 22272346, 2012). "Receiver operating characteristic curve analysis revealed that IRAK3 (mean AUC, 95%CI: 0.63, 0.54–0.72, P<0.05), TNFAIP3 (0.65, 0.56–0.73, P<0.01), SOD2 (0.69, 0.60–0.77, P<0.001), and TNFα (0.71, 0.62–0.78, P<0.001) were associated with metabolic syndrome." (PMID 22272346, 2012). "Weight loss was associated with an increase in IRAK3 and a decrease in SOD2, in association with a lowering of systemic inflammation and a decreasing number of metabolic syndrome components." (PMID 22272346, 2012). "Therefore, in this study, we selected rs12137855 in the LYPLAL1 gene, rs2854116 in the APOC3 gene and rs4880 in the SOD2 gene to investigate the association of three gene polymorphism, OS and their interaction with dyslipidemia." (PMID 36759651, 2023). "IL10 and SOD2 were lowly expressed in metabolic syndrome, and their expression levels were up-regulated after exercise (P < 0.05)." (PMID 37053002, 2023). "We further demonstrated that high GRS derived from combined SOD2, SOD3, GPX3, and GSTT1 polymorphisms have a strong association with such atherogenic dyslipidemia." (PMID 31396447, 2019). "Expression of Sod2, Txr1, Prdx3 and Gpx1 was altered by 3 months of exercise and/or severe dyslipidemia in 6-mo dyslipidemic mice." (PMID 27010651, 2016). "In the analysis of the interaction between OS and SOD2, it was found that those carrying all three genotypes in the OS group had a reduced risk of dyslipidemia compared to the non-OS group." (PMID 36759651, 2023). "Low IRAK3 in combination with high SOD2 expression is a marker of the metabolic syndrome." (PMID 22272346, 2012). "In rats that received sucrose for the brief lapse of time, the expression of endothelial nitric oxide synthase (eNOS) and superoxide dismutase 2 (SOD2), and total antioxidant capacity were decreased as much as in metabolic syndrome rats." (PMID 30717220, 2019). "Interestingly, the combination of low IRAK3 and high SOD2, a marker of mitochondrial oxidative stress was the strongest predictor of metabolic syndrome; it was even stronger than hs-CRP, the most widely used marker of systemic inflammation that was shown to be associated with metabolic syndrome." (PMID 22272346, 2012).